MIR3667 (microRNA 3667)
Synonyms: hsa-mir-3667
Gene: MicroRNA gene on chromosome 22 (49,543,393 to 49,543,466, reverse strand). Ensembl gene ENSG00000264139.
Homologues: Orthologues: chimpanzee MIR3667 (100% identical).